OR52P1 (olfactory receptor family 52 subfamily P member 1 (gene/pseudogene))
Description:
Odorant receptor.
Synonyms: OR52P1P; OR11-66
Gene: Protein-coding gene on chromosome 11 (5,726,502 to 5,727,464, forward strand). Ensembl gene ENSG00000181109.
Subcellular location: Cell membrane
Homologues: Orthologues: mouse Or52p1 (47% identical), rat Or52p1 (47% identical), dog OR52P1 (46% identical), rabbit OLFR656 (46% identical). Paralogues in human: OR52L1 (39% identical), OR52N4 (34% identical), OR52A5 (33% identical), OR52A1 (33% identical), OR52N5 (33% identical), OR52E2 (33% identical), OR52E5 (33% identical), OR52E8 (33% identical), OR52K1 (33% identical), OR52D1 (32% identical), OR52K2 (32% identical), OR52M1 (32% identical), and 39 more.